CYP11B2 (cytochrome P450 family 11 subfamily B member 2)
Diseases named in the same sentence as CYP11B2 in open-access papers (continued):
Sharing a sentence is not in itself a finding about the gene and the disease.
adrenocortical carcinoma (13 papers, 2012 to 2025). "CYP11B2 expression was detectable in HAoSMCs albeit at lower levels than in human adrenocortical carcinoma H295 cells." (PMID 28515448, 2017). "Other investigators reported that HDL2, very-low-density lipoprotein (VLDL) and glyco-oxidized VLDL can induce Cyp11B2 expression and stimulate steroid production in a human adrenocortical carcinoma cell line, NCI H295R." (PMID 28302174, 2017). "Supporting this, PCP4/PEP19 overexpression has been found to increase the transcription of a CYP11B2 reporter gene in adrenocortical carcinoma cells that produce aldosterone." (PMID 25153723, 2014). "We have previously shown that the PPARγ agonist pioglitazone inhibited both Ang II- and potassium-mediated aldosterone synthase gene (CYP11B2) transcriptional activation via Ca2+/calmodulin-dependent kinase (Ca2+-CaM-CaMK) inhibition in H295R cells derived from human adrenocortical carcinoma." (PMID 28800627, 2017). "We found that PFAS increased aldosterone synthase (CYP11B2) gene expression by three-fold and doubled aldosterone secretion and cell and mitochondria reactive oxygen species (ROS) production over controls (p < 0.01 for all) in human adrenocortical carcinoma cells HAC15." (PMID 37298327, 2023). "Overexpression of CASZ1 reduces aldosterone synthase (CYP11B2) and aldosterone levels in adrenocortical carcinoma cells (H295R-S2), suggesting that it probably inhibits CYP11B2 expression and the consequential aldosterone synthesis." (PMID 37509718, 2023). "As H295R cells are also derived from human adrenocortical carcinoma, it is plausible that NURR1 also plays an indispensable role in CYP11B2 transactivation in the cells." (PMID 28904869, 2017).
adrenocortical tumors (12 papers, 2013 to 2024). "CYP11B2 residing in the same region has been associated with adrenocortical tumor development." (PMID 27876019, 2016). "Subgroup analysis analyzing 51 uPA with CYP11B2-stained adrenocortical tumors showed outcomes consistent with our main results." (PMID 34572353, 2021). "The CYP11B2-stained adrenocortical tumor was detected in 100% of 165 adrenals with uPA harboring Sanger sequencing-identified mutations." (PMID 34572353, 2021). "CYP11B2-stained adrenocortical tumor was detected in 51 (68%) of 75 adrenals with uPA; 11 with cNGS-identified mutations and 40 without." (PMID 34572353, 2021). "In human adrenocortical neoplasms, CYP11B2 mRNA expression significantly and positively correlated with NURR1 mRNA expression, but not with NGFIB mRNA expression." (PMID 28904869, 2017). "However, our subgroup analysis analyzing only uPA with CYP11B2-stained adrenocortical tumors showed outcomes consistent with the main results." (PMID 34572353, 2021). "In addition, we firstly demonstrated that in the zona glomerulosa and adrenocortical neoplasms, CYP11B2-positive aldosterone-producing cells were less senescent than CYP11B2-negative or non-aldosterone producing cells." (PMID 34070051, 2021). "Of the remaining 24 (32%) adrenal glands with CYP11B2-negative adrenocortical tumors, 10 were associated with cNGS-identified mutation carriers and 14 had no cNGS-identified mutation." (PMID 34572353, 2021). "Several studies have suggested that the overproduction of steroid hormones in adrenocortical tumors might be resulted from the disordered expression of steroidogenic enzymes, such as aldosterone synthase (CYP11B2)." (PMID 24376526, 2013). "Importantly, past studies demonstrated that no aldosterone-driver mutation was detected in CYP11B2-negative adrenocortical tumors from PA patients." (PMID 34267727, 2021). "Thus, our aim was to analyze the expression profile of four key proteins involved in the steroidogenesis cascade, namely StAR protein, CYP11B1, CYP11B2 and CYP17A1, in different types of adrenocortical tumors." (PMID 32751564, 2020). "CYP11B2 did not manifested diagnostic potential for ACC, but it could be used to evaluate the function status and located the secreting area of aldosterone-secreting adrenocortical neoplasms." (PMID 38802933, 2024). "The adrenal contains two distinct adrenocortical tumors (an APA and a CYP11B2-negative tumor) which exist close to each other." (PMID 34267727, 2021). "Additionally, one patient in our study had a CYP11B2-negative adrenocortical tumor and one APCC on his section, indicating that APCC rather than the adrenocortical tumor found by CT may be responsible for the aldosterone overproduction." (PMID 34631800, 2021).
glucocorticoid-remediable aldosteronism (12 papers, 2013 to 2025). "Familial hyperaldosteronism type I (FH type I or GRA, glucocorticoid remediable aldosteronism) is caused by a hybrid CYP11B1/CYP11B2 gene inherited as an autosomal dominant trait." (PMID 29642543, 2018). "Four forms of FH are recognized, with type I (glucocorticoid remediable aldosteronism) due to a hybrid CYP11B1/CYP11B2 gene being the most common." (PMID 39821533, 2025). "Familial hyperaldosteronism type I (FH-I) is caused by the unequal recombination between the 11beta-hydroxylase (CYP11B1) and aldosterone synthase (CYP11B2) genes, resulting in the generation of a CYP11B1/B2 chimeric gene and abnormal adrenal aldosterone production." (PMID 23938178, 2013). "Gene fusions leading to constitutive expression of aldosterone synthase (encoded by CYP11B2), a rate-limiting enzyme in aldosterone biosynthesis, cause Glucocorticoid-Remediable Aldosteronism (GRA)." (PMID 25907736, 2015). "For example, glucocorticoid-remediable aldosteronism (GRA) is an autosomal disorder that occur when the promoter region of 11 β-hydroxylase gene (CYP11B1) and the coding regions of the aldosterone synthase (CYP11B2) gene unequally crosses over on chromosome 8q." (PMID 36329155, 2023).
diabetes (11 papers, 2006 to 2023). "Only age, gender, and CYP11B2 genotype were shown to be independent factors for association to diabetes." (PMID 24549414, 2014). "Thus, it was confirmed that a 1.4-fold increase in the odds for diabetes in subjects with C allele of CYP11B2 [Odds ratio 1.40 (95 % CI 1.04–1.90, p = 0.029)]." (PMID 24549414, 2014). "A multivariate logistic regression showed that age, gender, and CYP11B2 genotype were independent factors for association to diabetes, the DM risk of CC/CT to TT being 1.40 (95 % CI 1.04–1.90, p = 0.029)." (PMID 24549414, 2014). "It is therefore tempting to speculate, that vascular CYP11B2 could also contribute to osteoinductive remodeling of vascular tissue during diabetes." (PMID 28515448, 2017). "Results of these studies show that hypoxia is involved in cerebral edema, tumorigenesis, myocardial ischemia and diabetes in human being, and some genes including Endothelin 1 (EDN1), Erythropoietin (EPO) and Aldosterone synthase (CYP11B2) are reported as the key genes of hypoxia adaptation." (PMID 31239472, 2019).
adrenal tumors (10 papers, 2019 to 2024). "In APA patient with KCNJ5 mutations, opened calcium channels and the overexpression of CYP11B2 lead to excessive aldosterone secretion from the adrenal tumor." (PMID 35311227, 2022). "The adrenal tumor from the present case showed diffuse CYP11B2 immunoreactivity." (PMID 38505749, 2024). "Somatic mutations in both genes were also reported in the subsequent study using CYP11B2 IHC-guided targeted NGS, but those mutations were detected in CYP11B2-negative adrenal tumors from APA patients." (PMID 33920271, 2021). "Functionality of human adrenal tumors is inferred by CYP11B1 (cortisol synthase) expression, CYP11B2 (aldosterone synthase) expression, or both." (PMID 39387578, 2024). "Intriguingly, mutations in aldosterone-driving genes were still observed in 10 of those 24 CYP11B2-negative adrenal tumors in our cohort." (PMID 34572353, 2021). "Among those 24 CYP11B2-negative adrenal tumors, at least one APN or APM could be found in tissues adjacent to the adrenal tumor." (PMID 34572353, 2021).
heart failure (10 papers, 2012 to 2025). Inability of the heart to pump blood at an adequate rate to meet tissue metabolic requirements. "We predict that DNA methylation at CpGs 1 and 2 is a key determinant of the CYP11B2 mRNA levels in the heart, and that hypomethylation of the CYP11B2 promoter causes an aberrant increase in the CYP11B2 gene expression in the pathophysiology of cardiac hypertrophy, heart failure, or cardiomyopathy." (PMID 33925539, 2021). "Despite the central role of aldosterone in heart failure progression and risk for AF in heart failure, the relationship between the CYP11B2 −344C allele and AF in African Americans remains unknown." (PMID 23936266, 2013). "However, the role of MRAs in heart failure patients with the CYP11B2 −344 CC genotype-associated AF risk has yet to be ascertained." (PMID 23936266, 2013). "The implication of our findings that CYP11B2 genotype is associated with both AF risk and elevated aldosterone is that CYP11B2 may be a useful biomarker to identify heart failure patients at risk for AF in whom aldosterone antagonism may attenuate such risk." (PMID 23936266, 2013). "Clinical data, echocardiographic measurements, and a genetic sample for determination of CYP11B2 -344T>C (rs1799998) genotype and genetic ancestry were collected from 194 self-reported African Americans with chronic, ambulatory heart failure." (PMID 23936266, 2013). "The objective of this study was to examine the extent to which aldosterone synthase genotype (CYP11B2) and genetic ancestry correlate with atrial fibrillation (AF) and serum aldosterone in African Americans with heart failure." (PMID 23936266, 2013). "In fact, while mRNA levels of aldosterone synthase (CYP11B2) are about 100 to 10,000 times lower in the normal human heart than in the human adrenal gland, the aldosterone synthase expression has been found to be elevated in patient with heart failure." (PMID 26084817, 2015).
Obesity (9 papers, 2015 to 2025). Accumulation of substantial excess body fat. "We speculate that obesity-associated hyperleptinemia is a likely responsible factor, as leptin may act directly on adrenal glomerular cells to increase CYP11B2 expression and enhance aldosterone production through calcium-dependent mechanisms." (PMID 37049573, 2023). "The obesity risk increased with GRK4 A486V, ACE, and SLC12A3 variants in boys, whereas it increased with GRK4 A486V and CYP11B2 variants in girls as sodium intake increased." (PMID 25768006, 2015).
atrial fibrillation (8 papers, 2012 to 2024). A disorder characterized by an electrocardiographic finding of a supraventricular arrhythmia characterized by the replacement of consistent P waves by rapid oscillations or fibrillatory waves that vary in size, shape and timing and are accompanied by an irregular ventricular response. "Characteristics of the investigated studies of the association of the CYP11B2 T-344C gene polymorphism and atrial fibrillation (AF)." (PMID 23209837, 2012). "A single-nucleotide polymorphism, rs1799998, in the aldosterone synthase gene, Cytochrome P450 Family 11 Subfamily B Member 2 (CYP11B2), has also been reported to associate with cardiovascular diseases, such as atrial fibrillation or intracranial large artery stenosis." (PMID 38732608, 2024). "The CYP11B2 gene -344C/T polymorphism is also associated with atrial fibrillation (AF)." (PMID 28078278, 2016). "Aldosterone synthase (CYP11B2) T-344C gene polymorphism was found to be correlated with atrial fibrillation (AF) risk." (PMID 23209837, 2012). "The aim of this study was to investigate the potential associations of angiotensin-converting enzyme (ACE) gene insertion/ deletion (I/D) and aldosterone synthase (CYP11B2) gene −344T/C polymorphisms with the risk and recurrence of lone atrial fibrillation (AF)." (PMID 23170137, 2012). "Therefore, we investigated the association of tSNPs in RAS gene (ACE gene rs8066114, AGT gene rs7539020, rs3789678, rs2478544, rs11568023, rs2478523, rs4762, rs699 and CYP11B2 rs3802230, rs3097) and atrial fibrillation in a Chinese Han sample." (PMID 25723521, 2015). "Moreover, miR-138 is proved to be downregulated in patients with atrial fibrillation (AF) and reverse the proliferation of AF via repressing CYP11B2." (PMID 35116078, 2022). "In addition, inhibiting aldosterone synthase (CYP11B2) with torsemide prevents atrial fibrosis and atrial fibrillation in mice." (PMID 37771726, 2023).
resistant hypertension (7 papers, 2020 to 2025). "Furthermore, gene-based association analysis in this study revealed that the CYP11B2 gene was significantly associated with resistant hypertension, supporting the GWAS results." (PMID 34593835, 2021). "On the other hand, our GWAS discovered a suggestive association with resistant hypertension in the CACNA1D and CYP11B2 regions using a Japanese population, with high prescription rates for calcium channel blockers and angiotensin receptor blockers." (PMID 34593835, 2021). "We identified a novel candidate locus at the DLGAP1 gene with susceptibility to resistant hypertension with genome-wide significant levels, and 18 loci, including CYP11B2 and CACNA1D, as having suggestive association with resistant hypertension in the Japanese population." (PMID 34593835, 2021).
familial hyperaldosteronism (6 papers, 2018 to 2024). "The other two forms of familial hyperaldosteronism are attributed to gene rearrangements involving CYP11B1/CYP11B2 (type I familial hyperaldosteronism) and potential alterations at 7p22 (type II familial hyperaldosteronism)." (PMID 29594118, 2018). "Rare germline variants of CYP11B2 (encoding aldosterone synthase), CLCN2 (encoding voltage-gated chloride channel ClC-2), KCNJ5, CACNA1H (encoding a subunit of T-type voltage-gated calcium channel CaV3.2), and CACNA1D have been reported in different subtypes of familial hyperaldosteronism." (PMID 31695023, 2019). "We emphasize key differences between CYP11B1 (11β-hydroxylase) and CYP11B2 (aldosterone synthase) and the onset of a hybrid enzyme – CYP11B1/CYP11B2 –, responsible for aldosterone formation in ZF under ACTH control, in “type I familial hyperaldosteronism” (dexamethasone suppressible)." (PMID 35263051, 2022).
Hypokalemia (6 papers, 2016 to 2025). An abnormally decreased potassium concentration in the blood. "The real cause of hypokalemia in individuals with PA is due to the fact that the CYP11B1/CYP11B2 hybrid gene is unknown; however, it may be connected to the fact that aldosterone secretion is regulated by ACTH instead of angiotensin II." (PMID 38495792, 2024).
Primary hyperaldosteronism (6 papers, 2020 to 2025). A form of hyperaldosteronism caused by a defect within the adrenal gland. "The development of specific antibodies against human CYP11B2 (aldosterone synthase) is present within the pathology reports of resected adrenals due to primary hyperaldosteronism." (PMID 40951055, 2025). "CYP11B2 expression was reported to be upregulated in PBMCs of primary hyperaldosteronism (PA) patients as compared to healthy subjects and patients with Aldo-producing adenoma." (PMID 38175924, 2024). "Assessment of immunohistochemical expression of CYP11B2 is the recommended method for identifying regions of aldosterone production in human adrenal glands with primary hyperaldosteronism." (PMID 39387578, 2024).
Hyperkalemia (5 papers, 2014 to 2026). An abnormally increased potassium concentration in the blood. "The function of CYP11B2 gene is closely related to growth and development, and some studies have shown that patients deficient in CYP11B2 from 4 to 11 months of age suffer from vomiting, slow weight gain, hyponatremia, hyperkalemia, and low aldosterone levels." (PMID 37762538, 2023).
pheochromocytoma (5 papers, 2015 to 2025). "The CYP11B2 mRNA levels and the methylation status in some pheochromocytomas were almost equal with those of NFAs." (PMID 39596027, 2024). "Next, the CYP11B2 methylation statuses in the adrenal medulla (n = 4) and pheochromocytomas (n = 7) were examined." (PMID 39596027, 2024). "CYP11B2 mRNAs were detected in three samples of pheochromocytomas and NFAs." (PMID 39596027, 2024). "The unmethylated CpGs of CYP11B2 were found in the adrenal medulla and pheochromocytomas." (PMID 39596027, 2024). "Gene expression of CYP11B2 was detected in the pheochromocytomas." (PMID 39596027, 2024). "Similarly, CYP11B2 was 2-fold upregulated in ZG next to a pheochromocytoma versus next to an APA and 7.8-fold higher on quantitative real-time polymerase chain reaction." (PMID 28416583, 2017). "The sparseness of CYP11B2 in ZG is a general phenomenon whether adjacent to an APA or to a pheochromocytoma." (PMID 25915569, 2015). "We analyzed the methylation status of the CYP11B2 genes in the adrenal medulla, pheochromocytomas, and non-functioning adrenal adenomas (NFAs)." (PMID 39596027, 2024). "However, some genes associated with steroid, organic hydroxy compound, and alcohol-related processes that were upregulated in ZG samples from phaeochromocytoma patients (eg, CYP11B2, CYP39A1, PLA2G1B, and SULT1E1), were not significantly upregulated in ZG samples from adrenals with an APA." (PMID 27777363, 2016).
cardiac hypertrophy (4 papers, 2019 to 2024). "Hypomethylation of the CYP11B2 promoter causes an aberrant increase in CYP11B2 gene expression, which induces cardiac hypertrophy or cardiomyopathy." (PMID 36982850, 2023). "Hypomethylation of the CYP11B2 promoter aberrantly increases CYP11B2 expression, which induces cardiac hypertrophy or cardiomyopathy." (PMID 39125667, 2024). "Experimental studies using rat cardiomyocytes reported that both endogenous and exogenous BNP reduced aldosterone synthase (CYP11B2) mRNA expression, which may lead to the inhibition of the RAAS and attenuation of cardiac hypertrophy and fibrosis." (PMID 31336656, 2019).
Cushing syndrome (4 papers, 2016 to 2022). Cushing's syndrome (CS) encompasses a group of hormonal disorders caused by prolonged and high exposure levels to glucocorticoids that can be of either endogenous (adrenal cortex production) or exogenous (iatrogenic) origin. "Inhibition of AGT by CYP11B2 has been shown using sheep adrenal homogenates as well as a human adrenal homogenate from a patient with Cushing's syndrome." (PMID 27057163, 2016).